APOC3 (apolipoprotein C3)
Diseases named in the same sentence as APOC3 in open-access papers (continued):
Sharing a sentence is not in itself a finding about the gene and the disease.
coronary heart disease (84 papers, 2009 to 2025). "Mendelian randomization studies have revealed that loss-of-function mutations in the APOC3 gene are associated with reduced plasma TG levels and a lower risk of coronary heart disease." (PMID 39684468, 2024). "Four rare variants in the coding region of apolipoprotein C3 (APOC3) that disrupt APOC3 function were found to be associated with lower plasma triglyceride levels and a reduced risk of coronary heart disease." (PMID 38336686, 2024). "For instance, HDL-containing APOC3 has been shown to be associated with a higher risk of coronary artery disease." (PMID 37286042, 2023). "Apolipoprotein C3 (ApoC3) acts as an independent risk factor for coronary heart disease, particularly when it is present as a component of ApoB lipoprotein." (PMID 35453604, 2022). "This has been supported by the fact that overexpression of the ApoC3 gene during a lifetime has been associated with increased risk of coronary artery disease, whereas reduction of plasma levels of ApoC3 reduces the risk of developing coronary atherosclerosis." (PMID 35584319, 2022). "The plasma levels of ApoC3 and lipoproteins that carry ApoC3 independently predict a higher risk of coronary heart disease in prospective human cohorts after adjusting for blood lipids." (PMID 35453604, 2022). "Polymorphism of the APOC3 gene appears to influence the risk of hyperlipidemia, and APOC3 concentration and triglyceride levels correlate strongly with risk of coronary artery disease." (PMID 35265678, 2022). "Several polymorphisms in the human APOC3 gene affect levels of plasma triglycerides, thereby influencing the risk of ischemic vascular disease and severity of coronary heart disease." (PMID 35265678, 2022). "Higher apoE levels in plasma HDL were previously found to be associated with lower coronary heart disease risk, but the coexistence of another apolipoprotein, apoC3, modified this lower risk." (PMID 32648923, 2020). "More recently APOC3 19X carrier status among other APOC3 mutations was associated with lower risk of coronary heart disease." (PMID 30255797, 2018). "The same APOC3 variant has previously been associated with lower triglyceride levels and coronary artery disease risk." (PMID 28787443, 2017). "Increased concentrations of APOC3 are an indicator of a risk factor for coronary heart disease and atherosclerotic lesions." (PMID 28163789, 2017). "Loss-of-function APOC3 mutations have been associated with lower levels of triglycerides and decreased coronary heart disease risk." (PMID 27114411, 2016). "A rare variant in APOC3(rs138326449) has been associated with triglyceride, very low–density lipoprotein, and high-density lipoprotein levels, as well as risk of coronary heart disease." (PMID 27114411, 2016). "In this regard, genetic studies have indicated that the LPL and APOC3 pathway is strongly associated with plasma TG as well as coronary artery disease, gathering a great deal of attention as a novel therapeutic target." (PMID 27039080, 2016). "On the whole, the article calls for numerous issues to be ironed out prior to claiming, or to refuting, significant effects of the three APOC3 variants on coronary heart disease susceptibility." (PMID 27329227, 2016). "By promoting micro-RNA-4271 binding, the T allele of rs4225 inhibits APOC3 translation and may lower the risk of coronary heart disease (CHD)." (PMID 39684468, 2024). "Moreover, subjects who have mutations of the ApoC3 gene causing loss of function have 40% reduction in risk of developing coronary artery disease." (PMID 35584319, 2022). "A case–control study suggested that the APOC3 3238 G allele might contribute to an increased risk of coronary artery disease as a result of its effect on TG and VLDL-C metabolism." (PMID 25994187, 2015). "A systematic review of 20 studies comprising 15,591 participants found that APOC3 Sst I and T-455C polymorphisms might be associated with coronary heart disease risk." (PMID 25994187, 2015).
coronary heart disease (continued). "A recent prospective case–control study also found that the APOC3 3238 G allele might contribute to an increased risk of coronary artery disease as a result of its effect on TG and VLDL-C metabolism." (PMID 25994187, 2015). "A recent meta-analysis reported the association between two APOC3 gene polymorphisms (SstI and T-455C) and increased risk of coronary heart disease (CHD)." (PMID 36689070, 2023). "Although several previous studies reported associations of APOC3 gene polymorphisms with the development of type 2 diabetes mellitus and coronary artery disease, limited information is available as to whether genetic variations in APOC3 predict HTN development." (PMID 30380775, 2018). "Finally, analysis of whole exome sequences of 3734 participants of European or African ancestry identified rare mutations disrupting APOC3 function associated with lower levels of plasma triglycerides and a reduced risk of coronary heart disease for carriers of these mutations." (PMID 28449691, 2017). "Therefore, it could be hypothesized that reduction in APOC3 that we observed after omega-6 and omega-3 fatty acids supplementation could have implications for coronary heart disease risk." (PMID 28163789, 2017). "Apolipoprotein C3 (APOC3) is another potential therapeutic target for coronary heart disease treatment." (PMID 37762360, 2023). "In patients with coronary heart disease, aerobic exercise for 8 weeks led to a significant decrease in serum concentrations of TG and apoC3 (apolipoprotein C3) when compared with baseline levels." (PMID 33692469, 2021). "Based on the findings from a Mendelian randomization study investigating the association between loss-of-function mutation in the APOC3 gene and ASCVD, APOC3 inhibition seems to reduce triglycerides and coronary heart disease events." (PMID 30453617, 2018). "In this study, the APOC3 gene was resequenced and we identified a common variant which located in the microRNA-binding site in APOC3 and would affect its expression and the risk of coronary heart disease (CHD)." (PMID 27624799, 2016). "The GENOCOR study identified −482 C > T of APOC3 as an additive biomarker for ischemic heart disease in an Italian cohort of ischemic patients." (PMID 25994187, 2015). "Similarly to APOA2-related pathways, diseases associated with APOC3 include apolipoprotein C-III deficiency and coronary heart disease." (PMID 39062058, 2024). "We conclude that therapies specifically aimed at decreasing plasma ANGPTL3, ANGPTL4, and APOC3 levels are expected to reduce the risk of coronary artery disease without raising safety concerns." (PMID 38895109, 2024). "Besides APOA1 and APOA2, Apolipoprotein C-III (APOC3, 79 amino acids) is also associated with coronary artery disease." (PMID 38973469, 2024). "We aimed to clarify the relationship between apolipoprotein C3 (apo-C3) and the vascular composition of lesion plaque in stable coronary disease (SCD) before percutaneous coronary intervention (PCI), and to investigate major adverse cardiovascular events (MACEs) within 4 years." (PMID 36008556, 2022). "Carriers with APOC3 mutations had a 40% lower risk of coronary heart disease, but no protective effect of APOC3 deficiency on atherogenesis was observed in knockout (KO) mice." (PMID 34922545, 2021). "Moreover, large scale population genetic studies indicated that loss of function mutations in APOC3 and APOA5 gene conferred decreased and increased risk of coronary artery disease (CAD), respectively." (PMID 31836003, 2019). "For example, loss-of-function mutations in apolipoprotein C3 (APOC3), which is an inhibitor of LPL, decrease the risk of coronary artery disease (CAD), while loss-of-function mutations in apolipoprotein A5 (APOA5), which is an activator of LPL, increases the risk of CAD." (PMID 27039080, 2016).
coronary heart disease (continued). "One protein-truncating variant in APOC3 without any assigned specific inheritance mode (rs138326449) was classified as pathogenic and associated with coronary artery disease and hyperalphalipoproteinemia by a single submitter in ClinVar (VCV000139560.3) and found in nine individuals." (PMID 34691145, 2021). "Triglycerides (TGs) are proatherogenic lipoproteins involving the risk of coronary heart disease (CHD), while apolipoprotein A5 (APOA5) and apolipoprotein C3 (APOC3) are main lipoproteins composing TG-rich lipoproteins." (PMID 26387083, 2015). "Based upon these previous findings on diabetes and coronary heart disease risk, two conditions strongly linked to NAFLD, we examined the association of apoA1 in HDL that contained or lacked apoC3 with liver fat content and NAFLD in the Multi-Ethnic Study of Atherosclerosis (MESA)." (PMID 33142714, 2020). "Previously, we showed that higher apoA1 in HDL that contained apoC3 is associated with a higher risk of type 2 diabetes and coronary heart disease, whereas higher apoA1 in HDL that lacked apoC3 was associated with a lower risk of type 2 diabetes and coronary heart disease." (PMID 33142714, 2020).
diabetes (71 papers, 2006 to 2025). "APOC3 plays a complex role in diabetes-associated CVDs, affecting lipid metabolism, vascular health, and islet cell function through its presence in diverse lipoproteins, including VLDL, intermediate-density lipoprotein, LDL, and HDL." (PMID 39684468, 2024). "In diabetes, high glucose, insulin, and insulin resistance can affect the lipid metabolism: for example, the apoC-III encoding APOC3 gene expression is decreased by insulin and stimulated by glucose." (PMID 36419110, 2022). "Epidemiological studies have established that plasma apoC-III levels are positively associated with diabetes, and that Apoc3/APOC3 gene transcription increases in rat and human hepatocytes under high glucose conditions and is inhibited by insulin." (PMID 33918571, 2021). "Increased levels of APOC3 in serum, plasma, and vitreous fluids have been associated with the occurrence and the severity of many metabolic disorders, including diabetes and DR." (PMID 32933222, 2020). "Elevated serum APOC3 in diabetes has been shown to be a risk factor for DR due to its atherogenic properties." (PMID 32933222, 2020). "A case–control study suggested that APOC3 1100 C/T was associated with increased risk of diabetes probably through mechanisms other than direct effects on TG." (PMID 25380998, 2014). "We observed significant associations for two APOC3 SNPs, m482 and 3u386, with cognitive and metabolic measures in subjects with diabetes in a Caribbean Hispanic population." (PMID 19424489, 2009). "In summary, we identified significant associations between APOC3 polymorphisms, impaired cognition and metabolic dysregulation in Caribbean Hispanics with diabetes." (PMID 19424489, 2009). "Our findings are novel in that they show that APOC3 silencing is not only more effective in the setting of diabetes and that the harmful effects of diabetes in the artery wall are largely mediated by APOC3, but also that APOC3 is a stronger predictor of CVD risk in individuals with diabetes." (PMID 40709279, 2025). "Moreover, mouse models of type 1 and type 2 diabetes demonstrate that APOC3 is a causal mediator of diabetes-associated atherosclerosis." (PMID 40709279, 2025). "Therefore, more targeted and efficient APOC3-inhibiting therapies are being actively pursued for comprehensive TG management and cardiovascular risk reduction in patients with diabetes." (PMID 39684468, 2024). "Importantly, APOC3 ASO treatment reduced diabetes-associated glomerular hypertrophy, glomerular perilipin 2 staining, macrophage accumulation, and lipid-loaded macrophage accumulation." (PMID 38743496, 2024). "Therefore, this review aims to provide an overview of the role of APOC3 in regulating cardiometabolic risk, particularly its effects on TG metabolism, and narrow the focus to its specific involvement in diabetes-associated CVDs." (PMID 39684468, 2024). "The review will also highlight the latest research on APOC3 in diabetic populations, including longitudinal studies tracking its levels over time, in order to offer a more integrated understanding of its contribution to the cardiovascular risk in diabetes." (PMID 39684468, 2024). "However, when the diabetic mice were treated with an antisense oligonucleotide (ASO) to APOC3 in vivo, the increased macrophage cholesteryl ester loading associated with diabetes was prevented while the heightened Il1b and Tnfa gene expression was unaffected." (PMID 32118048, 2020). "Di-sialylated APOC3 is associated with improved lipids in diabetes." (PMID 32933222, 2020).
diabetes (continued). "In summary, our results support an association between APOC3 genotype and cognition in people with diabetes, which may be mediated through established vascular disease risk factors." (PMID 19424489, 2009). "Ingenuity pathway analysis (IPA; Supplemental Excel 3) was used to compare leukocyte clusters across the two diabetes models and in diabetic mice with hepatic APOC3 silencing." (PMID 40709279, 2025). "Consistently, both diabetes models had elevated plasma APOC3 levels, consistent with our previous studies." (PMID 40709279, 2025). "APOC3 ASO also altered the LDL and TRL/RLP proteome in a manner characteristic of increased lipoprotein particle clearance, with reduced levels of APOCs and APOE, indicating that APOC3 ASO normalized the slowed RLP clearance in diabetes." (PMID 40709279, 2025). "As in ECs, diabetes enhanced inflammatory signatures, including antigen processing, integrins, and senescence signaling, which were prevented by hepatic APOC3 silencing, with response to lipopolysaccharide as a major predicted upstream regulator." (PMID 40709279, 2025). "Strengths of this study include the use of two distinct mouse models of diabetes to increase scientific rigor, and, similar to therapeutics considered for human cardiovascular outcome trials, use of liver-targeted APOC3 and ANGPTL3 GalNAc ASOs." (PMID 40709279, 2025). "Our results highlight important roles for TRLs and RLPs in atherogenesis in diabetes—and APOC3 as a therapeutic target for CVD prevention in diabetes." (PMID 40709279, 2025). "Consistently, upstream regulator analysis identified the top diabetes-induced regulators prevented by APOC3 ASO as responses to PPARγ and the LXRα/β agonist GW3965, master regulators of lipid metabolism." (PMID 40709279, 2025). "APOC3 is known to cause high TG levels, which is the reason for the increased incidence of CVD during diabetes." (PMID 39684468, 2024). "Silencing APOC3 prevented diabetes-augmented albuminuria, renal glomerular hypertrophy, monocyte recruitment, and macrophage accumulation, partly driven by reduced ICAM1 expression." (PMID 38743496, 2024). "In diabetes, decreased insulin, elevated saturated fatty acids, and carbohydrate surges (e.g., glucose and fructose) collectively upregulate APOC3, increasing TG levels and TRLs accordingly." (PMID 39684468, 2024). "Together, these factors disrupt lipid metabolism and exacerbate CVD risk in diabetic populations, underscoring the critical role of APOC3 in managing diabetes-related CVDs." (PMID 39684468, 2024). "Beyond its involvement in lipid metabolism, APOC3 is crucial for regulating TG levels and modulating lipoprotein lipase (LPL) activity, both of which are key components in the pathogenesis of diabetes-associated CVDs." (PMID 39684468, 2024). "Ultimately, this review supports the development of therapeutic strategies targeting APOC3 reduction as a preventive approach for diabetes-related CVD." (PMID 39684468, 2024). "To investigate if APOC3 plays a role in kidney disease in people with type 2 diabetes, we analyzed plasma levels of APOC3 from the Veterans Affairs Diabetes Trial." (PMID 38743496, 2024). "We have recently demonstrated APOC3 silencing using an antisense approach results in a dramatic reduction in triglycerides and diminished diabetes-accelerated atherosclerosis." (PMID 37378396, 2023). "Patients with diabetes who have the apolipoprotein C3 gene (APOC3) m482 AA genotype exhibit impaired EF compared with those who have the AG/GG genotype." (PMID 32973635, 2020). "We examined whether APOC3 single nucleotide polymorphisms (SNPs) m482 (rs2854117) and 3u386 (rs5128) were related to cognitive measures, whether the associations between cognitive differences and genotype were related to metabolic differences, and how diabetes status affected these associations." (PMID 19424489, 2009).